HPSE (heparanase)
Description:
Endoglycosidase that cleaves heparan sulfate proteoglycans (HSPGs) into heparan sulfate side chains and core proteoglycans. Participates in extracellular matrix (ECM) degradation and remodeling. Selectively cleaves the linkage between a glucuronic acid unit and an N-sulfo glucosamine unit carrying either a 3-O-sulfo or a 6-O-sulfo group. Can also cleave the linkage between a glucuronic acid unit and an N-sulfo glucosamine unit carrying a 2-O-sulfo group, but not linkages between a glucuronic acid unit and a 2-O-sulfated iduronic acid moiety. It is essentially inactive at neutral pH but becomes active under acidic conditions such as during tumor invasion and in inflammatory processes. Facilitates cell migration associated with metastasis, wound healing and inflammation. Enhances shedding of syndecans, and increases endothelial invasion and angiogenesis in myelomas. Acts as a procoagulant by increasing the generation of activation factor X in the presence of tissue factor and activation factor VII. Increases cell adhesion to the extracellular matrix (ECM), independent of its enzymatic activity. Induces AKT1/PKB phosphorylation via lipid rafts increasing cell mobility and invasion. Heparin increases this AKT1/PKB activation. Regulates osteogenesis. Enhances angiogenesis through up-regulation of SRC-mediated activation of VEGF. Implicated in hair follicle inner root sheath differentiation and hair homeostasis.
Synonyms: Hpa1; HPA; HPR1; HPSE1; HSE1
Tractability: Small molecule: a structure with a bound ligand is known; a high-quality ligand is known; it belongs to a druggable protein family. Antibody: its Gene Ontology location is reachable by antibodies, with high confidence; UniProt places it where antibodies can reach, with medium confidence; UniProt predicts a signal peptide or a membrane-spanning region. PROTAC: ubiquitination databases record sites on it; a small molecule that binds it is known. Other modalities: a drug acting on it is in phase 2 or 3 trials.
Target class: Enzyme; Hydrolase
Chemical probes: PD007798
Gene: Protein-coding gene on chromosome 4 (83,292,461 to 83,335,153, reverse strand). Ensembl gene ENSG00000173083.
Subcellular location: Lysosome membrane; Secreted; Nucleus
Subcellular location (Human Protein Atlas): Nucleoplasm; Vesicles; Predicted to be secreted
Pathways (Reactome):
Immune System: Neutrophil degranulation
Metabolism: HS-GAG degradation
Gene Ontology:
Molecular function: heparanase activity; protein binding; syndecan binding; beta-glucuronidase activity; hydrolase activity, acting on glycosyl bonds
Biological process: cell-matrix adhesion; heparan sulfate proteoglycan catabolic process; positive regulation of blood coagulation; positive regulation of osteoblast proliferation; positive regulation of phosphatidylinositol 3-kinase/protein kinase B signal transduction; positive regulation of vascular endothelial growth factor production; regulation of hair follicle development; angiogenesis involved in wound healing; proteoglycan metabolic process; establishment of endothelial barrier; heparin proteoglycan metabolic process; positive regulation of hair follicle development; protein transmembrane transport; response to antibiotic; vascular wound healing; wound healing
Cellular component: lysosome; nucleoplasm; nucleus; extracellular matrix; extracellular region; lysosomal lumen; plasma membrane; specific granule lumen; lysosomal membrane; membrane; membrane raft
Genetic constraint (gnomAD): Loss-of-function variants: 31 observed, 39.25 expected, observed/expected ratio (o/e) 0.79, 90% interval 0.59 to 1.07. The upper end of that interval is the gene's LOEUF score, 1.07, which puts it in group 4 of 6, group 1 being the genes least tolerant of losing a copy. Missense variants: 466 observed, 453.82 expected, observed/expected ratio (o/e) 1.03, 90% interval 0.95 to 1.11. Synonymous variants: 184 observed, 188.14 expected, observed/expected ratio (o/e) 0.98, 90% interval 0.87 to 1.11.
Homologues: Orthologues: chimpanzee HPSE (99% identical), macaque HPSE (95% identical), dog HPSE (83% identical), rabbit HPSE (81% identical), mouse Hpse (76% identical), rat Hpse (75% identical), guinea pig HPSE (72% identical), pig HPSE (62% identical), tropical clawed frog hpse (53% identical), zebrafish hpse (50% identical), Drosophila melanogaster CG14309 (22% identical). Paralogues in human: HPSE2 (43% identical).
Diseases named in the same sentence as HPSE in open-access papers:
HPSE is named in the same sentence as 281 diseases in open-access papers, as found by Europe PMC text mining. Sharing a sentence is not in itself a finding about the gene and the disease. The quoted sentences say what the papers report.
breast carcinoma (103 papers, 2008 to 2025). "Recently, a meta-analysis demonstrated that HPSE expression was upregulated in most human breast cancer specimens and was associated with larger tumours, metastasis, histological tumour grade, and poor survival." (PMID 37297024, 2023). "HPSE expression was associated with reduced HS deposition and increased metastatic potential of breast cancer in patient samples." (PMID 37297024, 2023). "The aim of this study was to utilise an HPSE-deficient strain of the well-established MMTV-PyMT murine mammary carcinoma model (MMTV-PyMTxHPSE−/− mice) to investigate the role of HPSE in early establishment, progression, and metastasis of mammary tumours." (PMID 37297024, 2023). "HPSE has been associated with breast cancer progression, as supported by extensive in vitro and in vivo data, as well as numerous clinical investigations." (PMID 37297024, 2023). "In stage I breast cancer patients, a strong HPSE staining was associated with shorter overall survival rates." (PMID 34461608, 2021). "Here, we showed that some of these molecular mechanisms underlie the role of heparanase in increasing breast cancer cell survival." (PMID 34050190, 2021). "Heparanase is undetected in normal breast epithelium but its expression is induced in human breast carcinoma, associated with increased tumor metastasis and larger tumor size." (PMID 29464068, 2018). "An additional report implicated high levels of heparanase in resistance of metastatic breast cancer models to the small-molecule tyrosine kinase inhibitor of HER2 and EGFR, lapatinib, through the activation of a compensatory EGFR-dependent pathway." (PMID 30413079, 2018). "A Recent publication, analyzing the results obtained in several independent patient cohorts, showed that high levels of heparanase are associated with poor 5-year survival in breast cancer patients." (PMID 29464068, 2018). "Together, these findings suggest that high HPSE expression is associated with more aggressive biological characteristics in breast cancer." (PMID 28388549, 2017). "HPSE expression is elevated and associated with clinical characteristics in several types of carcinomas in addition to breast cancer." (PMID 28388549, 2017). "High rates of heparanase in circulating lymphocytes have been associated with recurrence in breast cancer patients, and a decrease in plasmatic levels has also been associated with therapeutic response in children with Hodgkin lymphoma." (PMID 26488476, 2015). "Heparanase gene regulation is also modulated by estrogen, which is an important risk factor for breast cancer." (PMID 23984412, 2013). "M402, a HS mimetic designed to inhibit multiple factors implicated in tumor-host cell interactions, including heparanase, showed some survival benefit in an orthotopic 4T1 murine mammary carcinoma model." (PMID 23300607, 2012). "In human breast carcinoma, heparanase-1 expression is associated with larger tumor size and lymph node metastasis." (PMID 23056402, 2012). "Heparanase activity has been correlated with cell invasion associated with breast cancer metastasis, a consequence of structural modification of HS that alters the extracellular matrix." (PMID 20652010, 2010). "Over-expression of heparanase in breast carcinoma cells (MDA-MB-231) was associated with a marked decrease in the expression of MMP family members, yielding a mirror image of the results obtained with the Hpse-KO mice." (PMID 19360105, 2009). "However, our efforts to define the kinetics of mammary tumour lesion-associated HPSE expression suggest that HPSE expression remains at a consistent level throughout mammary tumour development in MMTV-PyMT mice." (PMID 37297024, 2023). "Therefore, it is conceivable (confirmed by at least 2 databases) that a high HPSE expression is an independent risk factor, and is associated with poor prognosis in bladder and breast cancer." (PMID 34461608, 2021).
breast carcinoma (continued). "Since heparanase exerts properties to enhance insulin-induced proliferation in breast carcinoma cells in vitro, authors have reported a relevant association between lymph node metastases and the simultaneous existence of both hyperglycaemia and heparanase expression." (PMID 34070058, 2021). "Together, our data provide a novel immunological perspective on the mechanisms underlying breast cancer progression, and indicate that HPSE may serve as a biomarker for immune infiltration and prognosis in breast cancer." (PMID 34461608, 2021). "In addition, our data show that the high HPSE expression is an independent risk factor in bladder and breast cancer, indicating that HPSE can be used as a prognostic biomarker for bladder and breast cancer." (PMID 34461608, 2021). "MiR-1258 changes are directly linked to the expression of heparanase, which is an established prometastatic enzyme found in BM in breast cancer cells that degrades chains of heparan sulfate to alter the cytoskeleton and makes it easier for cells to cross the BBB40,41." (PMID 30224667, 2018). "Furthermore, we found that in stage I breast cancer patients strong heparanase staining is associated with shorter overall survival." (PMID 29464068, 2018). "According to the meta-analysis and TCGA data, we found that heparanase expression was up-regulated in most breast cancer specimens, and elevated heparanase expression was associated with increased lymph node metastasis, larger tumor size, higher histological grade, and poor survival." (PMID 28388549, 2017). "Indeed, a large number of studies have clearly linked heparanase expression with the process of tumorigenesis and invasion in a wide number of malignancies, including breast cancer." (PMID 24632672, 2014). "Although a significant correlation of heparanase overexpression is coupled with the progression of breast cancer, the underlying mechanisms remain unclear." (PMID 24632672, 2014). "A number of cancer therapeutics under development have been designed to target heparanase and recent identification of micro RNA mechanisms linked to brain metastatic breast cancer through heparanase control offers further rationale to develop heparanase-based therapeutics." (PMID 23300607, 2012). "In addition, HPSE overexpression accelerated the obesity-associated breast cancer progression." (PMID 34461608, 2021). "Therefore, we analyzed whether the HPSE expression was associated with immune infiltration levels in bladder and breast cancer." (PMID 34461608, 2021). "Here, we used the findings of a large pooled analysis and a prospective clinical trial in order to examine whether heparanase is associated with the outcome in breast cancer and to establish the role of heparanase in cell survival following chemotherapy in ER+ breast cancer." (PMID 34050190, 2021). "The results that showed that heparanase-1 co-expressed with phosphoinositide 3-kinase adapter protein 1, sialic acid-binding immunoglobulin-like lectin 7, and leukocyte-associated immunoglobulin-like receptor 1 are directed related with immune system evasion during breast cancer progression." (PMID 33053017, 2020). "Altogether, these data, along with the recently reported ability of the enzyme to enhance INSR signaling in myeloma, prompted us to hypothesize that heparanase may play an important role in diabetes-associated breast cancer, facilitating tumor aggressiveness under hyperinsulinemic state." (PMID 28038446, 2017). "Given the involvement of heparanase in the pathogenesis of breast cancer, we investigated the effect of compound XII on breast tumorigenicity." (PMID 38334603, 2024). "Beyond its cytotoxic effects, β-elemene suppresses BC cell migration and invasion, rendering it a promising candidate for targeted heparanase-focused therapy in breast carcinomas." (PMID 38918989, 2024). "HPSE is a direct target of miR-1258; thus, miR-1258 is a tumor-suppressive miRNA in breast cancer BM that functions by upholding ECM integrity." (PMID 38194195, 2024).
breast carcinoma (continued). "Expression of miR-1258 in breast cancer BM cells inhibited the activity of heparanase (HPSE), a prometastatic enzyme that degrades components of the extracellular matrix (ECM) to increase cell motility, migration, and invasion." (PMID 38194195, 2024). "The use of MMTV-PyMTxHPSE−/− animals therefore enabled the investigation of the influence of HPSE expression on breast cancer metastasis." (PMID 37297024, 2023). "Although HPSE has been reported to promote the development of breast cancer, the precise role of HPSE in the early stages of mammary tumour development remains poorly defined." (PMID 37297024, 2023). "In this study, the well-established spontaneous mammary tumour-developing MMTV-PyMT murine model was utilised to examine the role of HPSE in breast cancer establishment, progression, and metastasis." (PMID 37297024, 2023). "Most studies on the role of HPSE in breast cancer have been conducted using in vivo models incorporating HPSE overexpression, the use of isolated breast cancer cells in vitro, or the use of human clinical samples." (PMID 37297024, 2023). "HPSE expression was shown to be regulated by estrogen in both in vitro and in vivo settings, suggesting its hormonal-driven regulation in breast cancer." (PMID 37297024, 2023). "Heparanase (HPSE) is an endoglycosidase enzyme that also increases the BBB permeability by disrupting endothelial junctions during breast cancer BM." (PMID 37190188, 2023). "Specifically, it has been demonstrated that miR−1258 can target heparanase and subsequently inhibit the cell−aggressive phenotype in breast cancer." (PMID 36982956, 2023). "A number of studies also linked heparanase activity to the augmented INSR signaling in several types of malignant tumors (i.e., myeloma, breast carcinoma, synovial sarcoma)." (PMID 38078007, 2023). "Overexpression of extracellular superoxide dismutase was shown to inhibit HPSE expression, which in turn reduced in vitro breast cancer cell growth and invasion." (PMID 37297024, 2023). "Heparanase (HPSE) has been widely implicated in enhancing the development and progression of solid tumours, including breast cancer." (PMID 37297024, 2023). "This leads authors to suggest that either single or dual inhibition of heparanase and SDC1 can suppress the risk of breast cancer (progression) in individuals (patients) with high mammographic density." (PMID 36980680, 2023). "HPSE has been found to be a common BM mediator in both melanoma and breast cancers, facilitating BM either through its endoglycosidase activity or through mechanisms unrelated to its enzymatic activity, respectively." (PMID 37190188, 2023). "HPSE also mediates breast cancer BM by regulating proteoglycans in an enzymatically independent manner." (PMID 37190188, 2023). "The use of the spontaneous mammary tumour-developing MMTV-PyMT mice provided an excellent model to understand the role of HPSE in promoting early mammary tumour establishment." (PMID 37297024, 2023). "Contrary to our current understanding, we observed that even though HPSE regulated tumour angiogenesis, the establishment, progression, and metastasis of mammary tumours in MMTV-PyMT animals were HPSE-independent." (PMID 37297024, 2023). "Attempts were made to investigate the role of HPSE in the early stages of mammary tumour development, as the current literature is primarily focused on disease in its later stages." (PMID 37297024, 2023). "In order to determine the expression of HPSE in mammary tumour lesions of MMTV-PyMT and MMTV-PyMTxHPSE−/− mice, an anti-HPSE IHC assay was performed." (PMID 37297024, 2023). "Several studies have reported regulatory activities of nuclear heparanase, such as the induction of mammary cancer cell differentiation, regulation of glucose metabolism in endothelial cells, and gene transcription." (PMID 36980232, 2023).